LEP (leptin)
Diseases named in the same sentence as LEP in open-access papers (continued):
Sharing a sentence is not in itself a finding about the gene and the disease.
breast adenocarcinoma (3 papers, 2016 to 2023). "Another study found that Sam68 has an important role in the metabolism of hormones insulin and leptin, as its role appears in the signal transduction pathways of these hormones in three different directions for breast adenocarcinoma cells." (PMID 37900073, 2023). "To investigate the role of leptin in canine mammary adenocarcinoma progression, we introduced leptin and Allo-aca into CHMp cells." (PMID 33255835, 2020). "We aimed to study the expression of Sam68 and its phosphorylation level upon insulin and leptin stimulation, and the role of Sam68 in the proliferative effect and signalling pathways that are activated by insulin or leptin in human breast adenocarcinoma cells." (PMID 27415018, 2016). "In this study, we investigated the concurrent effects of leptin on the lysosomal enzyme CTSA and the following effects on tumor cell proliferation and invasion capacity of CHMp, a canine mammary adenocarcinoma cell line." (PMID 33255835, 2020). "In the human breast adenocarcinoma cell lines MCF7, MDA-MB-231 and BT-474, Sam68 protein quantity and gene expression were increased upon leptin or insulin stimulation, as it was checked by qPCR and immunoblot." (PMID 27415018, 2016). "Therefore, in this study, we mainly focused on the alteration of metastasis of canine inflammatory mammary adenocarcinoma (CHMp) cells with leptin (with or without Allo-aca) and CTSA and further evaluated the alteration of CMA activity." (PMID 33255835, 2020).
breast benign disease (3 papers, 2013 to 2019). "For group H, the leptin level was higher in breast benign diseases patients than in healthy controls." (PMID 23826274, 2013). "However, it is not known whether leptin participates in the oncogenic transformation of fibrocystic disease." (PMID 27293305, 2016).
breast diseases (3 papers, 2013 to 2022). "In this regard, we observed that women with BMI > 25 kg/m2 within the BC group showed differences in the biochemical behavior of leptin, adiponectin, resistin, and adipsin levels compared to women without breast disease." (PMID 35627631, 2022).
calcification (3 papers, 2017 to 2021). Process by which organic tissue becomes hardened by the physiologic deposit of calcium salts. "More recently, it was reported that augmented serum leptin confers a much greater risk for development of calcific aortic vascular disease; this detrimental effect of leptin was found to increase as a function of age and reduced renal function." (PMID 34064112, 2021). "The inflammatory marker IL-6 delivers cut-off values for the cardiovascular and operative risk profile by significant correlation with IDDM, AHT, and severe coronary calcification whereas leptin and BMI are predictive for DSWI." (PMID 32685095, 2020).
Chagas disease (3 papers, 2015 to 2025). A parasitic infection caused by Trypanosoma cruzi. "The levels of adiponectin are associated with reduced sympathetic activity and increased parasympathetic activity and the levels of leptin are associated with increased sympathetic activity and reduced parasympathetic activity in subjects with Chagas’ disease and cardiac involvement." (PMID 26147101, 2015). "Therefore, leptin/adiponectin levels may vary according to the type of infection/phase of Chagas disease and metabolic imbalance." (PMID 38533504, 2024).
chronic asthma (3 papers, 2013 to 2025). An asthma that is characterized by the development of persistent airway inflammation and recurrent attacks of breathlessness and wheezing, which vary in severity and frequency. "In the chronic asthma model utilized in the present study, leptin did not alter BAL neutrophils, however, leptin did significantly decrease HDM-induced BAL lymphocyte numbers, suggesting an immunomodulatory role." (PMID 35610699, 2022).
chronic fatigue syndrome (3 papers, 2013 to 2025). "Interestingly, the present results contrast our earlier finding that the adipokine leptin is associated with self-reported fatigue in many people with chronic fatigue syndrome/myalgic encephalomyelitis." (PMID 26420016, 2015). "Further, a male patient with AN and probable myalgic encephalomyelitis/chronic fatigue syndrome responded favourably despite a leptin level corresponding to the 99th centile adjusted for sex, Tanner stage and BMI." (PMID 40616697, 2025).
chronic hepatitis (3 papers, 2015 to 2020). An active inflammatory process affecting the liver for more than six months. "In the current study we investigated this point, we found a significant increase in the serum levels of adiponecine, leptin and visfatin in HCV chronic hepatitis patients compared to normal control." (PMID 32212784, 2020). "Fatigue severity has been associated with high circulating levels of this gene’s protein product, leptin, in CFS and in chronic hepatitis." (PMID 26694930, 2015).
Clear Cell Renal Cell Carcinoma (3 papers, 2020 to 2021). "The objective of this study was to use IHC to compare leptin and leptin receptor expressions in clear cell renal cell carcinomas (ccRCC) in non-obese and obese patients to determine the association between these proteins with the clinicopathological features and prognosis of ccRCC." (PMID 32802842, 2020).
co-infections (3 papers, 2018 to 2025). "A significant increase in leptin levels was observed during E. histolytica, Strongyloides, and Giardia co-infections." (PMID 29868503, 2018). "Co-infection of E. histolytica and Strongyloides positively correlated with increased leptin suggests it promotes pathogen tissue invasion and pathogenicity." (PMID 29868503, 2018). "An independent t-test was utilized to determine the comparison of serum IL-10 and IL-6 levels, while a Mann-Whitney test was used to establish the comparison of serum leptin levels in leprosy patients with and without helminth co-infection." (PMID 41239264, 2025). "This study aimed to measure the serum levels of IL-10, IL-6, and leptin in leprosy patients with and without helminth co-infections." (PMID 41239264, 2025). "Infection with S. aureus and co-infection with P. aeruginosa and S. aureus had no influence on the level of leptin." (PMID 37111072, 2023).
colorectal polyps (3 papers, 2014 to 2023). "Leptin was strongly associated with number and type of colorectal polyps in this study population." (PMID 24465801, 2014).
dengue (3 papers, 2020 to 2023). "Obesity-induced leptin and resistin are known to be associated with many of the physiological abnormalities seen in dengue, including platelet dysfunction, vascular inflammation, myocardial injury, endothelial dysfunction, and capillary hyper-permeability." (PMID 33083561, 2020). "We determined the levels of leptin, resistin, omentin, adiponectin, as well as IFNβ, and NS1 using quantitative ELISA in patients with dengue fever (DF = 49) and dengue haemorrhagic fever (DHF = 22) at admission (febrile phase) and at the time of discharge (recovery phase)." (PMID 37676889, 2023). "We determined the levels of leptin, resistin, omentin, adiponectin, IFNβ, and NS1 in patients with dengue fever (DF) and dengue haemorrhagic fever (DHF) at admission (febrile phase) and at the critical phase." (PMID 37676889, 2023).
diverticulosis (3 papers, 2014 to 2023). "While increased leptin concentrations were associated with higher rates of diverticulosis (OR 2.4; 95% CI 1.4–3.9), low molecular weight adiponectin (OR 0.5; 95% CI 0.3–0.8) and sRAGE (OR 0.4; 95% CI 0.3–0.7) concentrations were inversely associated." (PMID 37725283, 2023). "Furthermore, leptin, which positively correlated with BMI and waist circumference, was positively associated with the odds of having diverticulosis." (PMID 24740401, 2014). "Leptin was also positively associated with diverticulosis (OR = 5.5, CI: 2.0–14.7)." (PMID 24740401, 2014). "Leptin levels were found to be positively associated with diverticulosis, and LMW adiponectin levels were inversely related to the presence of diverticulosis in asymptomatic men." (PMID 33167521, 2020). "The adipokines leptin and low molecular weight (LMW) adiponectin were significantly associated with the presence of diverticulosis." (PMID 24740401, 2014). "Males who exhibited the highest concentrations of leptin (>9 ng/ml) were 5.5 (CI: 2.0–14.7) times more likely to have diverticulosis than those who had concentrations of leptin below 4.5 ng/ml (p = 0.0007)." (PMID 24740401, 2014). "The identification of anthropometric (BMI and waist circumference) and serum analytes (sRAGE, leptin, LMW adiponectin) associated with diverticulosis may yield insight into the etiology of diverticular disease." (PMID 24740401, 2014). "The pattern of high BMI, waist circumference, leptin and C-peptide increased the odds of diverticulosis while the pattern of high levels of sRAGE and LMW adiponectin decreased the odds of diverticulosis." (PMID 24740401, 2014). "Therefore the strong positive association between leptin and diverticulosis, and the strong negative association between LMW and diverticulosis may be a result of their strong correlation with anthropomorphic measures." (PMID 24740401, 2014). "sRAGE, a highly novel marker, which was not correlated with leptin or adiponectin but was correlated with BMI and waist circumference, was inversely related to the presence of diverticulosis." (PMID 24740401, 2014). "This lack of correlation with the adipokines suggests a role for sRAGE in diverticulosis independent of the leptin/adiponectin signaling axis." (PMID 24740401, 2014).
follicular thyroid cancer (3 papers, 2012 to 2020). "Transcription was stimulated by leptin in anaplastic, papillary, and follicular carcinomas of genes involved in invasion, such as matrix metalloproteinases (MMPs)." (PMID 32645835, 2020). "In follicular thyroid cancer cells, leptin had more dramatic effects in gene expression than those of OB3; for example leptin increased the expression of PCNA and c-Myc in FTC236 cells but decreased the expression of PCNA, c-Myc and MCL-1 in FTC238 cells." (PMID 27050378, 2016). "Interestingly, both OB3 and leptin inhibited the invasion in follicular thyroid cancer FTC236 cells." (PMID 27050378, 2016). "In follicular thyroid cancer (FTC236) cells, both OB3 and leptin significantly reduced the expression of GLUT2 and GLUT5, but only OB3 increased GLUT1 expression." (PMID 27050378, 2016). "In follicular thyroid cancer patients, expression of leptin or Ob-R expression are not correlated with recurrence or metastasis during the follow-up." (PMID 27050378, 2016). "This is consistent with our own experimental observations that leptin did not stimulate proliferation in follicular thyroid cancer cells." (PMID 27050378, 2016). "In contrast, both papillary and follicular thyroid cancer cells treated with leptin did not increase invasiveness, compared to the untreated control." (PMID 27050378, 2016). "This indicates that neither OB3 nor leptin affected the expression of heterodimeric integrin αvβ3, an adhesion factor in papillary and follicular thyroid cancer cells." (PMID 27050378, 2016).
frontotemporal dementia (3 papers, 2021 to 2025). Frontotemporal dementia (FTD) comprises a group of neurodegenerative disorders, characterized by progressive changes in behavior, executive dysfunction and language impairment, as a result of degeneration of the medial prefrontal and frontoinsular cortices. "Altered peripheral levels of leptin have been recently reported in patients with ALS and frontotemporal dementia (FTD), which exists on a continuous clinical spectrum with ALS." (PMID 34638645, 2021).
gallbladder disease (3 papers, 2017 to 2020). "Furthermore, gallbladder diseases such as cholelithiasis are associated with serum leptin levels in humans and dogs." (PMID 33167521, 2020). "Moreover, we previously evaluated the relationship between leptin and gallbladder disease in dogs." (PMID 31238989, 2019). "Leptin and its receptor play several physiological roles in the canine gallbladder, and the dysregulation of leptin might play a role in the pathogenesis of gallbladder diseases such as gallbladder mucocele." (PMID 29088261, 2017).
gastric ulcer (3 papers, 2019 to 2023). An ulcerated lesion in the mucosal surface of the stomach. "In ischemia reperfusion- and ethanol-induced gastric ulceration models, rats administered leptin [10 μg/kg body weight (BW)] showed significantly attenuated gastric lesions." (PMID 33935782, 2021). "Consistently, in rats with either indomethacin-induced or stress-induced gastric ulcer, leptin treatment (10 μg/kg BW, 6 h) significantly decreased the gastric ulcer index and neutrophil infiltration." (PMID 33935782, 2021). "Low post-exercise appetite has been observed in athletic horses (box-housed) and is suggested to be associated with the hormone’s active ghrelin, adiponectin, and leptin, and/or gastric ulcers." (PMID 31739646, 2019). "Meanwhile, the beneficial effects of several peptides (i.e., amylin, cholecystokinin, leptin, and stable gastric pentadecapeptide BPC 157, suggested as an acting mediator of the dopamine brain-gut axis) were included in the dopamine gastric ulcer story." (PMID 38139825, 2023). "Meantime, the beneficial effects of several peptides (i.e., amylin, cholecystokinin, leptin, and stable gastric pentadecapeptide BPC 157 (suggested as the acting mediator of the dopamine brain-gut axis)) further extended the dopamine gastric ulcer story." (PMID 38139825, 2023).
gingivitis (3 papers, 2014 to 2025). A disorder involving inflammation of the gums; may affect surrounding and supporting structures of the teeth. "According to the results of the univariate LR analysis, elevated leptin and calprotectin levels and reduced adiponectin levels were significantly associated with the presence of gingivitis (p < 0.01)." (PMID 41300847, 2025). "According to the results of the ROC analysis, leptin, calprotectin, and adiponectin were identified as significant biomarkers for the diagnosis of gingivitis (p < 0.01)." (PMID 41300847, 2025). "In contrast, the effect of leptin levels on gingivitis was not statistically significant in the multiple LR analysis (p > 0.05)." (PMID 41300847, 2025).
glaucoma (3 papers, 2018 to 2023). Increased pressure in the eyeball due to obstruction of the outflow of aqueous humor. "Several mechanisms are linked to the higher IOP, including: 1) Increased retrobulbar fat diminishes aqueous outflow and results in a higher IOP, 2) Alterations in plasma levels of ghrelin and leptin can increase IOP and induce glaucoma." (PMID 35476846, 2022).
glomerulopathy (3 papers, 2015 to 2025). "One proposed mechanism leading to glomerulopathy is an increase in leptin levels." (PMID 25710704, 2015).
Granuloma (3 papers, 2015 to 2022). A compact, organized collection of mature mononuclear phagocytes, which may be but is not necessarily accompanied by accessory features such as necrosis. "However, the leptin-treated diet-D infected group showed a significant increase in the size and number (164 ± 8; p ≤ 0.05) of granulomas compared to its untreated group." (PMID 29116252, 2017). "Additionally, leptin is essential for negatively modulating the immune response against infection; for example, the absence of leptin in ob/ob mice leads to a higher formation of granulomas in mice infected with mycobacteria." (PMID 35682832, 2022).
gynecological cancer (3 papers, 2014 to 2025). "To explore the biological mediators linking adiposity factors to cancer risk, we examined the association of two adipokines, leptin and adiponectin, with the gynecological cancers." (PMID 25115836, 2014). "To further investigate the molecules mediating the relationship of adiposity factors to the cancer risk, we examined the associations of two adipokines, leptin and adiponectin, with the development of gynecological cancers." (PMID 25115836, 2014). "In the nested case-control study, case subjects with incident gynecological cancer had a significantly higher level of leptin and a significantly lower level of adiponectin in plasma at enrollment as compared with control subjects." (PMID 25115836, 2014). "However, leptin levels have been found to be elevated in breast and gynecological cancer patients due to factors other than cachexia, limiting the potential of leptin as a universal biomarker for identifying cachectic patients." (PMID 28177923, 2017).
H1N1 influenza (3 papers, 2016 to 2024). "Notably, one recent study found that baseline elevation of circulating leptin contributes to the development of H1N1 influenza induced lung injury in mice, which improved upon administration of anti-leptin antibody." (PMID 27835678, 2016). "Moreover, previous studies on H1N1 influenza reported an impaired production of IFN-α and IFN-β due to leptin, a hormone produced by the adipose tissue that is known to regulate fat storage." (PMID 37047702, 2023).
hemorrhagic stroke (3 papers, 2013 to 2022). A stroke caused by a bleed on the brain. "On the one hand, literature data describe leptin as a pro-inflammatory mediator and a risk biomarker for first hemorrhagic stroke." (PMID 35624723, 2022).
hepatitis B (3 papers, 2016 to 2025). "Previous study showed that serum leptin was elevated in patients with hepatitis B patients, and apoM expression was lower in leptin deficient ob/ob mice." (PMID 27927202, 2016).
hypovitaminosis D (3 papers, 2021 to 2025). "• Serum 25(OH)D was negatively correlated to serum leptin (r = −0.20, p = 0.027) and to subcutaneous abdominal fat (r = −0.23, p = 0.012). • BMI > 30 kg/m2 was a risk factor of hypovitaminosis D [25(OH)D <30 ng/ml] (OR 4.3, 95% CI 1.21–5.3, p = 0.018)." (PMID 34422722, 2021). "Τhis is the first report of a physiological association of leptin and IL-6 under Athonian fasting conditions and sufficient vitamin D status, which has been reported to affect the interplay of adipokines, particularly in the existence of hypovitaminosis D, which is very common in these populations." (PMID 40218903, 2025).
idiopathic pulmonary arterial hypertension (3 papers, 2012 to 2023). A sporadic form of pulmonary arterial hypertension (PAH) characterized by elevated pulmonary arterial resistance leading to right heart failure. "Similarly in another study, adiponectin, leptin, and endothelin-1 levels in idiopathic pulmonary arterial hypertension (IPAH) patients’ serum were found to be higher than those in healthy volunteers." (PMID 30791536, 2019).
juvenile idiopathic arthritis (3 papers, 2020 to 2025). Juvenile idiopathic arthritis (JIA) is the term used to describe a group of inflammatory articular disorders of unknown cause that begin before the age of 16 and last over 6 weeks. "It is reported that plasma and SF leptin were significantly correlated in juvenile idiopathic arthritis." (PMID 34457118, 2021). "In children with active juvenile idiopathic arthritis, alterations in adiponectin, leptin, and tenascin C were observed, characterized by increased plasma ADPN and decreased LEP and TNC plasma concentrations, suggesting their involvement in the pathogenesis of JIA." (PMID 41011290, 2025).
laryngeal carcinoma (3 papers, 2017 to 2023). Carcinoma that arises from the laryngeal epithelium. "Gallina reported that leptin was associated with recurrence of malignancy in laryngeal cancer." (PMID 36010881, 2022). "The presence of N/OFQ in upper airway carcinoma, and specifically in larynx carcinoma, has not yet been thoroughly investigated; however, some studies on the role of some neuropeptides (e.g., leptin) in laryngeal cancer encouraged the research on this topic." (PMID 37623462, 2023).